MSI2 (musashi RNA binding protein 2)
Diseases named in the same sentence as MSI2 in open-access papers (continued):
Sharing a sentence is not in itself a finding about the gene and the disease.
breast carcinoma (17 papers, 2014 to 2025). "Alternatively, Bcl-xl, a stemness marker lost after MSI2 knockdown has been associated with doxorubicin resistance in breast cancer." (PMID 40843174, 2025). "MSI2 has also been reported to suppress tumor epithelial-to-mesenchymal transition (EMT) progression in breast cancer, and low MSI2 expression is associated with poor outcomes for breast cancer patients; however, the underlying mechanisms have not been fully investigated." (PMID 32448269, 2020). "Enlarged nuclei indicative of metastasis in breast cancer were observed in Scr-treated clone #1 tumor-bearing mice; however, MSI2 knockdown restored the karyoplasmic ratio to normal." (PMID 39990676, 2025). "MiR‐7 has been shown to inhibit the proliferation, migration and invasion of colorectal cancer, breast cancer, papillary cancer and many other types of cancer cells, which agrees with the tumorigenic roles of Msi2 and HuR." (PMID 34877814, 2022). "We had shown that, in breast cancer cells, apigenin interacts with the RNA-binding proteins MSI2 and hnRNPA227, which regulate alternative splicing of DR5 and c-FLIP, respectively, and also with Hsp70." (PMID 33731677, 2021). "In breast cancer, the MSI2 protein level is markedly elevated and promotes the expression of estrogen receptor 1, which facilitates the malignant biological behavior of breast cancer cells." (PMID 34047477, 2021). "A recent study of breast cancer suggested that MSI2 can also suppress epithelial-to-mesenchymal transition (EMT) progression in TNBC MDA-MB-231 cells by regulating the translation of epithelial genes." (PMID 32448269, 2020). "Another study of luminal breast cancer demonstrated that MSI2 promotes luminal cell growth, although survival analysis indicated that high MSI2 expression is associated with favorable outcomes for breast cancer patients." (PMID 32448269, 2020). "MSI2 in the TNBC tissues was downregulated compared with that in ANTs and other breast cancer subtypes, and loss of MSI2a expression in TNBC was associated with poor patient survival." (PMID 32448269, 2020). "MSI2 directly regulates estrogen receptor by binding to ESR1 resulting in breast cancer cell growth." (PMID 32139710, 2020). "Another study demonstrated that the antitumorigenic effects of DBC2 in breast cancer were specifically dependent on promoting polyubiquitination-mediated proteasomal degradation of MSI2 in breast cancer cell lines." (PMID 32448269, 2020). "For example, MSI2 is highly expressed in ER(+) breast cancer, and its expression is significantly correlated with ESR1 expression, which affects the growth of breast cancer cells, by changing the function of ESR1." (PMID 30881302, 2019). "Initially, we used activation of a (transcription factor)/LEF-1-dependent luciferase reporter construct (TOPFLASH) in MCF7 (a luminal breast cancer cell line) to assess the effect of MSI2 overexpression on Wnt signalling." (PMID 29093438, 2017). "Matching the pattern observed in primarytumors, we observed higher Msi1 and Msi2 expressionin luminal breast cancer lines than in basal lines." (PMID 25380226, 2014). "MSI2 promotes cell growth in breast cancer via increasing estrogen receptor 1 protein stability." (PMID 31952541, 2020). "These divergent functions of MSI2, especially in breast cancer, suggest that it might have additional molecular mechanisms that need to be further investigated." (PMID 32448269, 2020). "It is also reported that MSI2 can also inhibit the progress of EMT in breast cancer, and the low expression of MSI2 is related to the poor prognosis of breast cancer patients." (PMID 36059653, 2022). "Nonetheless, MSI2 was also reported to act as an upstream regulator of ESR1, leading to luminal breast cancer proliferation and invasion, whereas MSI2 overexpression was associated with a better prognosis in breast cancer." (PMID 32448269, 2020). "MSI2 has been reported to maintain protein and RNA stability to regulate ESR1 function in breast cancer." (PMID 31888685, 2019).
breast carcinoma (continued). "To study the roles of MSI2 isoforms in the regulation of TNBC cell proliferation and metastasis, we first detected the mRNA expression levels of MSI2a and MSI2b and the protein expression level of MSI2a in seven different breast cancer cell lines." (PMID 32448269, 2020). "In addition to above controversy, MSI2 predicts unfavorable outcome in AML and hepatocellular cancer, whereas Numb is a better prognostic markers in breast cancer and salivary gland carcinomas." (PMID 27092875, 2017). "In addition, MSI2 directly regulates estrogen receptor 1 (ESR1) expression, which is a well-known therapeutic target, by binding to the specific sites in ESR1 RNA and increasing the stability of ESR1 protein, thus affecting the growth of breast cancer cells." (PMID 36059653, 2022).
lung cancer (16 papers, 2013 to 2025). A malignant neoplasm involving the lung. "Therefore, Sox2 and Msi2 have poor diagnostic specificity in lung cancer." (PMID 23683495, 2013). "This is in line with findings in lung cancer implicating MSI2 in DNA damage repair and in triple-negative breast cancer regarding double knockdown of MSI1 and MSI2." (PMID 40843174, 2025). "We further confirmed that MSI2 plays an important role in the development of lung cancer by knocking down MSI2 and RESCUE MSI2 to detect cell clone formation and proliferation levels." (PMID 38645664, 2024). "In summary, MSI2 appears to play a significant role in the tumorigenesis and radiosensitivity of lung cancer cells." (PMID 38645664, 2024). "This work explored the effects and mechanisms of MSI2 on radiosensitivity of lung cancer cells, including the confirmation of MSI2 on radiosensitivity, the regulatory role on DNA damage repair, and the key targets and interrelationships." (PMID 38645664, 2024). "Our current study revealed that MSI2 is vital for regulating the radiosensitivity of lung cancer cells." (PMID 38645664, 2024). "This study provides novel insights into the potential application of MSI2 as a new target in lung cancer radiotherapy." (PMID 38645664, 2024). "Our findings demonstrated that the reduction in MSI2 expression significantly impeded the clonogenic survival of lung cancer cells post‐irradiation, with the suppressive effect becoming more pronounced with increasing radiation doses." (PMID 38645664, 2024). "To further elucidate the mechanism by which MSI2 and RBM17 induce radioresistance in lung cancer cells, we performed immunofluorescence detection of MSI2 and RBM17 in A549 cells at 0, 0.5, 4, 8, 12, and 24 h post‐irradiation with 8 Gy." (PMID 38645664, 2024). "In this study, we first demonstrated that MSI2 plays a key function in regulating the radiosensitivity of lung cancer." (PMID 38645664, 2024). "Knockdown MSI2 had a radiosensitizing effect on lung cancer and MSI2 played a radioresistant role in lung cancer radiotherapy." (PMID 38645664, 2024). "To delve deeper, we conducted Kaplan‒Meier survival analysis of MSI2 mRNA expression levels and lung cancer prognosis using Kaplan‒Meier plotter." (PMID 38645664, 2024). "The expression of MSI2 is negatively correlated with overall survival in cancer patients, and the knockdown of MSI2 inhibits tumorigenesis and increases radiosensitivity of lung cancer cells." (PMID 38645664, 2024). "In the light of published papers, we have validated proteomic analysis data that suggested VEGFR2 regulation upon MSI2 depletion in murine lung cancer." (PMID 37173995, 2023). "It was previously indicated that MSI2 protein is increased in liquid and solid tumors, of which lung cancer is one of them." (PMID 37173995, 2023). "MSI2 is a member of the Musashi family of RNA-binding proteins, which are overexpressed in various tumors, including ovarian, pancreatic, bladder, and lung cancers." (PMID 35288483, 2022). "Actually, the oncogenic role of MSI2 in colon cancer was supported by an independent report using the knockdown assay; more NSCLC cell lines are needed to distinguish the role of MSI2 in colon and lung cancers." (PMID 35153752, 2021). "MSI2 is upregulated in metastatic-competent lung cancer cell lines, and aggressively metastatic patient tumors have upregulated MSI2." (PMID 31694854, 2020).
lung cancer (continued). "In lung cancer, the expression of Sox2 and Msi2 was 90% and 94% respectively, and more than 85% of tissues was diffusely positive for both of the markers." (PMID 23683495, 2013). "With the exception of OCT4, other markers Bmi1, CD133, CD44, Sox2, Nanog and Msi2 mRNA and protein were abundantly expressed in lung cancer." (PMID 23683495, 2013). "Additionally, MSI2 promotes increased invasion of lung cancer cells by regulating the TGFβR1/SMAD3 signaling pathway, which can be used as an effective biomarker for the prognosis of NSCLC." (PMID 39969091, 2025). "The stem cell fate determinant Musashi-2 (Msi2) is one such signal that has been shown to be critical in development as well as advanced cancers; however, its role in lung cancer is not well understood." (PMID 40047406, 2025). "To determine whether Musashi regulates the growth and progression of aggressive lung cancer we first determined whether Msi2 is expressed in stem cells of the distal lung." (PMID 40047406, 2025). "In summary, we suggested that MSI2 may impact the radiation‐induced DNA damage response and, consequently, the radiation sensitivity of lung cancer cells through its interaction with ATR." (PMID 38645664, 2024). "We are interested in the radioresistance of MSI2, and knocking down the radiosensitizing effect of MSI2 on lung cancer, either by gene therapy or chemical inhibitor development, has practical clinical applications for improving the efficacy of radiotherapy in NSCLC." (PMID 38645664, 2024). "We further elucidated the effects of MSI2 on radiosensitivity of lung cancer cells and its patterns, clarified the regulatory role of MSI2 on DNA damage repair in lung cancer cells, and revealed the molecular mechanism of MSI2 on radiosensitivity of lung cancer cells." (PMID 38645664, 2024). "Our published paper suggested that MSI2 depletion in murine lung cancer cell line 344SQ may decrease VEGFR2 protein levels based on RPPA data." (PMID 37173995, 2023). "Similarly, upregulation of MSI2 is an indicator of increased metastatic potential in lung cancer and hepatocellular carcinoma, and is proposed to stimulate EMT through stimulation of canonical Wnt signaling." (PMID 31694854, 2020). "In addition, MSI2 seems to be involved in patients’ prognosis, resulting as prognostic factor in gastric and cervical cancer; in lung cancer, MSI2 emerged as a novel therapeutic target." (PMID 31878037, 2019). "The purpose of this study is to investigate the differential expression and clinical significance of seven stem-cell-associated markers (Bmi1, CD133, CD44, Sox2, Nanog, OCT4 and Msi2) in lung cancer, providing new targets for the diagnosis and treatment of lung cancer." (PMID 23683495, 2013). "RBM17 and MSI2 may synergistically promote radioresistance in lung cancer." (PMID 38645664, 2024). "In addition, MSI-2 stimulates migration and invasion of bladder cancers by activating the JAK2/STAT3 signaling pathway, and indirectly downregulates tight junction–associated claudins to increase lung cancer cell invasion and metastasis." (PMID 29073938, 2017). "In addition to these known regulators, a number of genes not previously implicated in lung cancer were found to be significantly downregulated following Msi2 inhibition, suggesting that they may play a role in tumor growth." (PMID 40047406, 2025). "We found that knockdown of RBM17 disrupted the interaction between MSI2 and ATR post‐irradiation and increased the radiosensitivity of lung cancer cells." (PMID 38645664, 2024). "Based on the experimental results presented above, we posit that MSI2 enhances DNA damage repair through interactions with RBM17 and ATR, thereby increasing the radiation resistance of lung cancer cells." (PMID 38645664, 2024).
lung cancer (continued). "Knockdown of MSI2 not only significantly increased the number of γ‐H2AX foci after irradiation, but also significantly increased the length of DNA tails in lung cancer cells, which indicated that knockdown of MSI2 increased the degree of DNA damage, or inhibited the DNA damage repair." (PMID 38645664, 2024). "When lung cancer cells are irradiated after knocking down MSI2, there is not enough MSI2 to enter the nucleus after DNA damage occurs, and it cannot interact with RBM17 and ATR to activate ATR, resulting in DNA damage repair not proceeding smoothly." (PMID 38645664, 2024). "Therefore, we conclude that MSI2 positively regulates both VEGFR2 mRNA and protein levels and also regulates VEGF-A mRNA translation in human lung cancer cells." (PMID 37173995, 2023). "MSI2 is highly expressed in a variety of cancers, including HCC and lung cancer." (PMID 32828126, 2020). "In this study, we applied RT-PCR to examine the differential expression of Bmi1, CD133, CD44, Sox2, Nanog, OCT4 and Msi2 mRNA in bronchoscopic biopsy specimens from lung cancer and non-cancer patients." (PMID 23683495, 2013). "When MSI2 is knocked down or inhibited in lung cancer cells, there is not enough MSI2 to enter the nucleus after DNA damage, so it cannot interact with RBM17 and ATR to activate ATR, which will not successfully complete DNA damage repair and increase tumor cell death." (PMID 38645664, 2024). "However, the positive expression rates of CD133, CD44, Sox2, OCT4 and Msi2 did not correlate with age, gender, histological type, stage and differentiation of lung cancer." (PMID 23683495, 2013). "When lung cancer cells undergo DNA damage after radiation exposure and emit certain signals, RBM17 may sense these signals, translocate into the nucleus, facilitate the entry of MSI2, and subsequently interact with ATR, activating ATR along with CHK1 and other downstream molecules." (PMID 38645664, 2024). "However, the mRNA relative levels of Bmi1, CD133 and CD44 by RT-PCR were not significantly different between lung cancer and non-malignant lung tissues analyzed by Mann–Whitney U test, nor were the expression rates of CD44 and Msi2." (PMID 23683495, 2013).
colorectal cancer (15 papers, 2016 to 2024). A primary or metastatic malignant neoplasm that affects the colon or rectum. "Furthermore, in a loss–rescue screening based on the MSI2 knockout cancer cells, palmatine was identified as a functional MSI2 antagonist inhibiting the MSI2-dependent growth of colorectal cancer cells." (PMID 35153752, 2021). "However, it is unclear whether MSI2 regulates cell death in colorectal cancer (CRC), especially the underlying mechanisms and biological effects in CRC ferroptosis remain elusive." (PMID 38041016, 2023). "Moreover, our results imply that cytoplasm MSI‐2 overexpression might be a biomarker for screening patients with colorectal cancer to have the risk of liver metastasis." (PMID 26775684, 2016). "The Musashi-2 (MSI-2) gene is overexpressed in various tumors, including colorectal cancer, and plays an important role as an oncogene in carcinogenesis and tumor progression." (PMID 39028420, 2024). "In particular, MSI2 is ubiquitously elevated and proposed as a novel biomarker and therapeutic target of hematopoietic malignancies and colorectal cancers." (PMID 35153752, 2021). "In a loss–rescue screening, palmatine was identified as a functional MSI2 antagonist inhibiting the MSI2-dependent growth of colorectal cancer cells." (PMID 35153752, 2021). "Our findings not only indicated MSI2 as a promising therapeutic target of colorectal cancer but also provided a small molecule palmatine as a direct and functional MSI2 antagonist for cancer therapy." (PMID 35153752, 2021). "MSI2, MACC1 and TAGLN were reported to be associated with ovarian cancer, colorectal cancer and esophageal cancer, respectively." (PMID 31640538, 2019). "Another important finding is the candidate target mRNAs of MSI2 in colorectal cancer." (PMID 35153752, 2021). "Therefore, inhibition of both MSI1 and MSI2 are required to fully abrogate tumor growth in colorectal cancer cell lines." (PMID 29064439, 2017). "MSI2 is highly expressed in leukemia and colorectal cancers." (PMID 29064439, 2017). "However, the precise role of MSI2 in regulating PTMs and tumor immunity in colorectal cancer (CRC) remains unclear." (PMID 38347600, 2024). "The RBP Musashi-2 (MSI2) has been identified as an oncoprotein in diverse tumors, including blood, breast, pancreatic, prostate, lung and colorectal cancers." (PMID 38041016, 2023). "In colorectal cancer initiation and maintenance, a recent study demonstrated the functional redundancy between MSI1 and MSI2." (PMID 30097032, 2018). "In conclusion, we developed MSI2 knockout cancer cells and demonstrated that MSI2 is required for the survival of colorectal cancer HCT116 cells but not NSCLC A549 cells." (PMID 35153752, 2021). "In the study, we created MSI2 knockout cancer cells and demonstrated that MSI2 is required for the survival of colorectal cancer HCT116 cells but not non-small cell lung cancer A549 cells." (PMID 35153752, 2021). "Through the profiling of gene expression upon the depletion of MSI2, we identified 38 genes in colorectal cancer cells with altered protein expression versus the unchanged RNA level; all of them were specifically regulated by MSI2 in the context of colon cancer but not NSCLC cells." (PMID 35153752, 2021). "In addition, our data provide some insights into the roles of MSI‐2 in colorectal cancer, and warrant further investigation into the specific functions of MSI‐2 protein, which is likely to find a new therapeutic target for colorectal cancer." (PMID 26775684, 2016).